ENSG00000268240 (novel transcript)
Gene: Long non-coding RNA gene on chromosome 19 (21,587,424 to 21,596,026, reverse strand). Ensembl gene ENSG00000268240.
Gene Ontology:
Biological process: SRP-dependent cotranslational protein targeting to membrane, signal sequence recognition
Cellular component: signal recognition particle, endoplasmic reticulum targeting